IGFBP3 (insulin like growth factor binding protein 3)
Diseases named in the same sentence as IGFBP3 in open-access papers (continued):
Sharing a sentence is not in itself a finding about the gene and the disease.
Shock (1 paper, 2024). The state in which profound and widespread reduction of effective tissue perfusion leads first to reversible, and then if prolonged, to irreversible cellular injury. "Other forms of acute stress, such as septic shock, have also been associated with an increase in IGF-I and IGFBP-3 levels within the first few days of hospital admission, and heavy exercise has been found to momentarily upregulate IGF-I production, both from the liver and other tissues." (PMID 39273528, 2024).
skin cancer (1 paper, 2016).
skin inflammations (1 paper, 2020). "Igfbp3 and Mir-17hg (Mir-17–92) have been shown to be associated with skin inflammations and their expression was initially decreased in Sox13-/- basal keratinocytes, but this pattern was flipped at 7wk." (PMID 32065580, 2020).
sleep-related breathing disorders (1 paper, 2024). "While the association between IGFBP-3 and sleep-related breathing disorders (SRBDs) in PWS remains unexplored, our study indicates that the heightened levels of IGF-1 and IGFBP-3 resulting from rhGH treatment do not adversely affect SRBDs." (PMID 38200464, 2024).
Solid Pseudopapillary Neoplasm of the Pancreas (1 paper, 2016). A low-grade malignant neoplasm that arises from the exocrine pancreas. "Eighteen cases of solid pseudopapillary neoplasms of the pancreas were evaluated for RNA expression levels of FLI1, DKK1, INPP5D (SHIP1), IGFBP3, PBK (TOPK), and BCL9 and BCL9L." (PMID 27539223, 2016).
Testicular atrophy (1 paper, 2006). Wasting (atrophy) of the testicle (the male gonad) manifested by a decrease in size and potentially by a loss of fertility. "The main IGFBPs were determined by Western-ligand-blot, showing changes in the pattern of IGFBPs with a significant increment of IGFBP3 in rats with testicular atrophy treated with IGF-I (Arbitrary Units, CO: 23.77 ± 0.48, AT: 23.01 ± 0.95, AT+IGF: 28.24 ± 1.11)." (PMID 16504030, 2006). "Interestingly, plasma IGF-I did not augment in rats with testicular atrophy treated with IGF-I, while IGFBP3 levels, that reduces IGF-I availability, was increased in this group (p < 0.05)." (PMID 16504030, 2006).
tongue squamous cell carcinoma (1 paper, 2022). A squamous cell carcinoma that arises from the tongue. "We previously found that IGFBP3 mRNA levels are higher in endophytic-type human tongue squamous cell carcinoma (TSCC) that is more invasive and more prone to metastasis than exophytic and superficial types." (PMID 35798794, 2022).
tongue tumors (1 paper, 2021). "Both WT and Igfbp3 KO mice showed primary tongue tumor formation at 100% incidence after 4-NQO exposure for three months." (PMID 33801272, 2021). "We further assessed the impact of IGFBP-3 on the metastatic activities of human HNSCC cells by utilizing orthotopic tongue tumor model of UMSCC38-shEV or UMSCC38-shBP3 in non-obese diabetic/severe combined immunodeficiency (NOD/SCID) mice." (PMID 33801272, 2021).
tonsillitis (1 paper, 2016). Inflammation of the tonsillar tissue. "This study aimed to determine the effect of adenotonsillectomy on IGF-1 and IGFBP-3 serum levels in patients with ATH or recurrent tonsillitis." (PMID 27738609, 2016).
Urethral stricture (1 paper, 2023). Narrowing of the urethra associated with inflammation or scar tissue. "In sum, Igfbp3/Smad pathway participates in driving the progressive exacerbation of urethral fibrosis and Igfbp3 might be a novel therapeutic target for urethral stricture." (PMID 37653219, 2023). "RNA-seq analysis suggested that Igfbp3/Smads might regulate the progressive FMT in urethral stricture." (PMID 37653219, 2023). "Similarly, our investigation unveiled elevated Igfbp3 levels in human urethral stricture tissue." (PMID 37653219, 2023).
vitreous haemorrhage (1 paper, 2022). "IGFBP3 and PDGF-BB levels were also strongly related to visual acuity, which may relate to the reduced acuity associated with vitreous haemorrhage, rather than other causes." (PMID 36473885, 2022).
tumor (383 papers, 1996 to 2026). "Consistent with single-cell RNA sequencing and spatial transcriptomics data, mIHC confirmed the presence of IGFBP3 in both tumor cells and cancer-associated fibroblasts within the TME of PDAC." (PMID 40443651, 2025). "Subsequent evaluation of the tumor immune microenvironment showed that IGFBP3 is primarily expressed in tumor cells and cancer-associated fibroblasts." (PMID 40443651, 2025). "According to various studies, the expression of IGFBP3 has been found to be associated with multiple types of cancer and exert different functions, which depend on the cellular environment and tumor type." (PMID 38326861, 2024). "It was inconsistently reported that high IGF-1 and IGFBP-2 and low IGFBP-3 circulating levels are associated with high cancer risk, poor prognosis, and tumor metastasis in several cancers." (PMID 38137390, 2023). "In a word, the results of this study are in agreement with the literature, which suggests that IGFBP3 was significantly correlated with tumor clinical characteristics and can act as a diagnostic biological marker of LIHC." (PMID 37397026, 2023). "Circulating levels of IGF-1, IGFBP-2, and IGFBP-3 were investigated for their association with tumor grade and stage." (PMID 38137390, 2023). "Based on previously reported studies, it has been documented that IL1B, CXCL1, CDK6, and IGFBP3 were closely associated with tumor radiosensitivity." (PMID 37468464, 2023). "IGFBP-3 therefore likely plays an important role in tumor metastasis and growth in TSCC, and identifying underlying mechanisms will facilitate the development of novel therapeutic strategies for targeting IGFBP-3, especially in endophytic-type TSCC." (PMID 35798794, 2022). "IGFBP3/5/6/7 expression was significantly elevated in pathological stages II–IV compared with pathological stage I. IGFBP3/5/7 expression was also significantly increased in advanced T-stage patients and was associated with tumor progression in STAD." (PMID 34745945, 2021). "In the animal model, a low IGFBP3 expression was associated with a more significant tumor progression, higher cancer invasion, and distant metastasis, while a high IGFBP3 expression was associated with tumor necrosis and apoptosis." (PMID 34824343, 2021). "In our previous study, xenografts with IGFBP3-expressing cell lines, P0, and P4-I (P4-pKG3226-hIGFBP3, a stable P4 transfectants expressing IGFBP3) showed growth arrest associated with the inhibition of vasculogenesis and tumor necrosis." (PMID 34824343, 2021). "The association between tumour IGFBP-3 and circulating IGFBP-3, functioning as the main carrier of IGF-I and IGF-II, is yet to be fully elucidated." (PMID 32093285, 2020). "The frequency of tumours with high IGFBP-3 expression was significantly higher in patients associated with poor responses to preoperative chemoradiotherapy than in patients with good responses (p = 0.028)." (PMID 32093285, 2020). "Having demonstrated that loss of GRP78 promotes the tumorigenic actions of IGFBP-3 in our in vitro experiments we re-grouped our clinical dataset into GRP78 low tumours with either low or high IGFBP-3 staining." (PMID 33352865, 2020). "Nuclear FAK is specifically linked to IGFBP3 through its interaction with Runx1, which leads to cell cycle progression and tumor growth regulation." (PMID 33240810, 2020). "Nevertheless, some studies have shown significant associations between tumour IGFBP-3 levels and cancer prognosis." (PMID 32093285, 2020). "Tumor-associated PSC possesses a lower expression of IGFBP3 and higher expression of IGFBP2 as compared to the normal PSC." (PMID 32414222, 2020). "In fact, IGF-1 and IGFBP-3 levels, as well as the IGF-1/IGFBP-3 ratio, are reported to be associated with cancer risk and tumor development." (PMID 30621039, 2019).
tumor (continued). "While no statistical difference and trend of serum CEA levels between different tumor differentiation were found, results of the present study are in accordance with the literature that IGFBP‐3 is associated with tumor clinical characteristics." (PMID 31218761, 2019). "IGFBP3 shows overexpression in association with markers of poor prognosis in many tumour types, including RCC." (PMID 31046666, 2019). "High IGF1 levels and both lower and higher levels of IGFBP3 are predictor risk factors for secondary tumour development in patients with HNSCC." (PMID 30594912, 2018). "Two studies found a positive association between tumor progression and IGFBP-3 suppression or deficiency, while another found tumor size to be smaller within mice that over-expressed IGFBP-3." (PMID 28361446, 2017). "The current meta-analysis suggests that the lower IGFBP-3 level is significantly associated with higher cancer risk, lower 3-year survival rate, more advanced tumor stages, and more distant metastasis." (PMID 27978831, 2016). "By contrast with these inhibitory and apoptotic effects of IGFBP-3, however, it appears that in some tissues IGFBP-3 functions as a tumor promoter as it is associated with poor patient outcomes." (PMID 26221601, 2015). "Methylation levels of all genes analyzed were significantly higher in tumor tissues compared to normal mucosa (p<0.0001); however, cancer-associated hypermethylation was most frequently observed for miR137 (86.7%) and IGFBP3 (83%) in CRC patients." (PMID 25127039, 2014). "IGFBP3 expression had a significant association with tumor location (p = 0.023), and a significant inverse association with venous invasion (p = 0.037)." (PMID 23962053, 2013). "IGFBP3 expression had a significant association with tumor location (χ2 test, p = 0.023), and a significant inverse association with venous invasion (Fisher’s exact test, p = 0.037)." (PMID 23962053, 2013). "It remains a distinct possibility that the strong tumor suppressive effect of IGFIR loss was mostly due to the high levels of IGFBP3." (PMID 24260413, 2013). "Klk1, Klk21, Klk24 and Klk27 have been linked to Igf1-regulated tumour survival through degradation of the Igf binding protein Igfbp3 in humans." (PMID 21961992, 2011). "Variants in the IGFBP-3 gene may influence these interactions, altering the protein’s ability to induce apoptosis and suppress tumor growth." (PMID 40493660, 2025). "Does the observed association between IGFBP3 expression and tumor stage simply reflect this fact?" (PMID 37397026, 2023). "In contrast, in some other cancers including prostate cancer and clear cell renal cell carcinoma increased tumor IGFBP-3 expression may be associated with poor patient outcomes." (PMID 35597813, 2022). "IGFBP3 can function as a tumor suppressor and is downregulated in some neoplastic tissues, but it nevertheless shows overexpression in association with markers of poor outcome in some tumor types." (PMID 32500027, 2020). "However, IGFBP3 exerted tumor‐promoting roles in other cancers and was associated with poor prognosis of patients." (PMID 31304688, 2019). "Interestingly, TAZ knockdown resulted in a marked increase in tumor suppressor IGFBP3 expression and complete inhibition of EMT‐associated VIM expression, but YAP did not influence the expression of these genes." (PMID 31633304, 2019). "Additionally, high IGFBP3 methylation levels in primary tumour were associated with recurrence (P = 0.004)." (PMID 30944663, 2019). "Collectively these data suggest that, in these xenograft models of human basal-like TNBC, a high nuclear IGFBP-3 level may be a poor prognostic feature, associated with high tumor proliferation and decreased apoptosis." (PMID 29623068, 2018). "Similarly, higher levels of IGFBP-3 have been associated with tumor progression and resistance to treatment due to the intranuclear roles of IGFBPs in transcriptional regulation, induction of apoptosis, and DNA damage repair." (PMID 29527228, 2017).
tumor (continued). "Importantly, IGFBP3, one of the genes upregulated in UCAPe cells, has been implicated in the suppression of oxidative stress to promote tumor growth." (PMID 28851898, 2017). "In addition, high levels of IGFBP-3 has been associated with low concentrations of estrogen receptor (ER) or progesterone receptor and large tumor size, suggesting a poor prognosis and decreased survival in cancer patients." (PMID 27562357, 2016). "Abnormal expression or malfunction of IGFBP3 is associated with tumor development and progression." (PMID 26540630, 2015). "Based on the datasets from Oncomine and Taiwan OSCC patients, we observed that the level of IGFBP3 mRNA was up-regulated in tumorous tissues and associated with the N stage of clinicopathological features, suggesting the role of IGFBP3 in lymph node metastasis of OSCC." (PMID 26540630, 2015). "Previously, we hypothesized that IGFBP-3 loss in both blood and tissues could be accounted for by degradation by tumour-produced proteases." (PMID 24905466, 2014). "Because IGFBP3 has an important role in tumor development, polymorphisms located in IGFBP3 might be potential markers in the evaluation of exposure of target organs to endogenous IGFBP3 on cancer risk." (PMID 23527244, 2013). "Similarly, IGFBP-3 promoter methylation in tumor cells has been linked to decreased survival in stage I NSCLC patients." (PMID 19549343, 2009). "Down-regulation of the Igfbp3 gene, encoding for the insulin growth factor binding protein, in Smad4+/E6sad ES and intestinal cells may also represent a relevant early step in tumor formation." (PMID 19014666, 2008). "However, the importance of high tumor IGFBP-3 levels in the progression of many cancer types remains unclear because there are some cancers in which IGFBP3 appears to act as a tumor suppressor gene, with low IGFBP-3 levels associated with poor patient outcome." (PMID 29623068, 2018). "Although IGFBP3 is epigenetically suppressed in some cancers, with an apparent tumor suppressor role, in other cancer types it shows high expression in association with high tumor grade and/or poor patient survival, although often the IGFBP-3 protein is located predominantly in the cytoplasm." (PMID 29623068, 2018). "However, methylation of IGFBP3 was associated with advanced tumour grade." (PMID 17453001, 2007). "Oestrogens transcriptionally downregulate IGFBPs in breast tissue and increase IGFBP-3 proteases, which may in part explain the inverse association between IGFBP-3 and ER expression, as well as perhaps reflecting the disruption of common pathways characteristic of poor prognostic tumours." (PMID 15642160, 2005). "For instance, promoter hypermethylation of insulin-like growth factor binding protein-3 (IGFBP-3), a tumor suppressor gene, has been associated with enhanced tumor growth and drug resistance." (PMID 40463874, 2025). "Since the spatial transcriptomics platform used in this research was the 10x Visium Cytassist version, with a resolution of 55μm, we conducted mIHC analysis to visually demonstrate the distance between high IGFBP3-expressing tumor cells and CD8+ T cells." (PMID 40443651, 2025). "IGFBP3 + ECs are enriched in tumor tissues, whereas collagen-producing ECs are more prevalent at the tumor-normal tissue interface, potentially contributing to the ECM." (PMID 41035074, 2025). "The in vivo data confirmed our in vitro results, with IGFBP3‐oe reversing the inhibition of tumour growth observed in FTO‐kd cells." (PMID 40621649, 2025). "We found that tumor cells with high IGFBP3 expression were surrounded by significantly fewer CD8+ T cells." (PMID 40443651, 2025).
tumor (continued). "The fibroblast-secreted IGFBP-3 subsequently acts on tumor cells to upregulate IL-17RB at the metastatic front in the tumor and promote invasion." (PMID 41226289, 2025). "Spatial transcriptomics further demonstrated that IGFBP3 expression varies across tumor subregions and microenvironmental contexts, indicating its regulation by diverse cellular components." (PMID 40443651, 2025). "A complex mechanism has been described where CRC-derived tumor cells secrete TGF-β1 which induces IGFBP-3 expression in pericytes." (PMID 41226289, 2025). "IGFBP3-high cells were predominantly localized in epithelial cells, primarily within the tumor core of PDAC." (PMID 40443651, 2025). "To validate these findings in vivo, we established a mouse model of subcutaneous LUAD by injection of A549 cells with IGFBP3‐oe alone or FTO‐kd and IGFBP3‐oe in nude mice, and measured tumour volumes every 5 days." (PMID 40621649, 2025). "Subcutaneous tumor formation experiments in nude mice also showed that IGFBP3 can promote cisplatin resistance in BCa in vivo." (PMID 41199784, 2025). "Our integrated analysis using TCGA and GEO datasets revealed that IGFBP3 exhibited the highest tumor-specific expression and prognostic relevance among all IGFBP family members." (PMID 40443651, 2025). "Beyond its relationship with IGF-1, the primary physiological function of IGFBP3 is to suppress cell proliferation and growth, a function that is exploited when used as a tumor-suppressive agent." (PMID 39886833, 2025). "FTO and IGFBP3 mRNA levels were both higher in tumour tissues than normal tissues, although the increase in IGFBP3 was not statistically significant." (PMID 40621649, 2025). "Other notable NET-related CSM and SP genes include previously discussed IGF-2 and IGFBP3 genes and genes related to the stromal component of the tumor (COL5A3, FN1, and NOTCH3)." (PMID 40522948, 2025). "The biological role of IGFBP3 was verified using immunohistochemical, immunofluorescence and mice orthotopic tumor model." (PMID 38326861, 2024). "Previous studies have demonstrated that IGFBP3 negatively modulate the insulin secretion and insulin signaling pathway, exerting inhibitory effects on tumor cell proliferation and progression." (PMID 38952983, 2024). "The expression of IGFBP3 and TPM1, on the other hand, has been closely associated with tumor cell growth and survival, further emphasizing the potential significance of these genes in the context of DLBCL." (PMID 38240686, 2024). "We established C57BL/6J mice brain orthotopic tumor model, observed that knockdown of IGFBP3 attenuated the growth of tumors at 21 days after tumor cell injection, and significantly improved the survival rate of mice." (PMID 38326861, 2024). "The tumor cells expression and blood serum levels of IGFBP3 are related to the survival of GBM patients." (PMID 38326861, 2024). "Upon cisplatin administration for another 19 days, tumor size in the IGFBP3 overexpression group was significantly reduced compared with that in the control vector group, suggesting enhanced cisplatin sensitivity." (PMID 38169528, 2024). "Among 148 upregulated genes, IGFBP3 (insulin-like growth factor-binding protein 3), a tumor suppressor, plays an important role in CRC tumorigenesis." (PMID 39261464, 2024). "When we examined all the cell populations in our dataset, we confirmed minimal IGFBP3 expression in RCC tumor cells as well as IGFBP5 expression in pericytes, which have an overlapping gene expression signature with arterial smooth muscle cells." (PMID 39516665, 2024). "Several studies have shown that IGFBP-3 has both tumor-suppressing and tumor-promoting effects according to the posttranslational modifications, assay methods, and cell types." (PMID 39272080, 2024). "Growth factors like IGF binding protein 3 (IGFBP3) have been studied given the role of the IGF-pathway in tumor cell proliferation, metastasis, and survival." (PMID 38254117, 2024).